NEFL (neurofilament light chain)
Diseases named in the same sentence as NEFL in open-access papers (continued):
Sharing a sentence is not in itself a finding about the gene and the disease.
CNS tumors (7 papers, 2010 to 2025). "Of the three genes examined, overexpression of HOXB13 was unique to MEPN, while overexpression of NEFL and PDGFRα was observed in other pediatric CNS tumors." (PMID 19793339, 2010). "In addition to MEPN and intracranial EPN, comparative gene expression analysis of HOXB13, NEFL and PDGFRα was expanded to include a variety of pediatric CNS tumors." (PMID 19793339, 2010).
mitochondrial disease (4 papers, 2021 to 2024). "Our results suggest that the combination of neurofilament light chain, fibroblast growth factor 21 and growth and differentiation factor 15 is useful in the diagnostic evaluation of mitochondrial disease." (PMID 33501425, 2021). "We measured serum neurofilament light chain, fibroblast growth factor 21 and growth and differentiation factor 15 in 26 patients with a genetically proven mitochondrial disease." (PMID 33501425, 2021).
genetic disorder (3 papers, 2018 to 2024). "Neurofilament light chain (NfL) has proved to be useful biomarker for PNP, given that it is related to metabolic and genetic disorders, but it has not been studied in SSc." (PMID 39156689, 2024).
autosomal dominant disease (1 paper, 2019). Autosomal dominant form of disease. "The first neurofilament-related CMT to be discovered was CMT2E, an autosomal dominant disease that can be caused by any of more than 20 different mutations distributed through the head, rod and tail domains of the NF-L encoding NEFL gene." (PMID 31097008, 2019).
NEFL also shares sentences with these, for which no sentence is quoted: concussion (31 papers); Parkinsonism (28); Encephalopathy (20); epilepsy (19); Anxiety (18); bipolar disorder (14); parkinsonian disorder (13); cardiovascular disease (12); primary progressive aphasia (12); ischemia (11); Down syndrome (10); kidney disease (10); Myelopathy (10); myopathies (10); type 2 diabetes (10); cognitive disorder (9); dyslipidemia (9); infarct (9); movement disorder (9); transient ischemic attack (9); autoimmune encephalitis (8); cerebral infarction (8); corticobasal degeneration (8); Cerebral atrophy (7); Cerebral ischemia (7); Creutzfeldt-Jakob disease (7); demyelination (7); primary progressive MS (7); psychotic disorder (7); Spinocerebellar ataxia type 3 (7).
A further 318 diseases each share a sentence with NEFL in 6 papers or fewer.